NLRX1 (NLR family member X1)
Diseases named in the same sentence as NLRX1 in open-access papers (continued):
Sharing a sentence is not in itself a finding about the gene and the disease.
diabetes (2 papers, 2019 to 2021). "We analyzed the effect of NLRX1 deficiency on diabetes development and the accompanied renal damage, inflammation, and fibrosis." (PMID 30908533, 2019). "We, therefore, assessed the role of NLRX1 in DN in a multiple low-dose streptozotocin (STZ) model of diabetes using wild type (WT) and NLRX1-deficient C57BL/6J male mice." (PMID 30908533, 2019). "Finally, an NLRX1 polymorphism (rs4245191), which predisposes patients to macrovascular complications and diabetic cerebral infarction, was identified as a risk factor for vascular complications of type 2 diabetes mellitus in the southern Han Chinese population." (PMID 33525671, 2021). "The multiple low-dose STZ model was successful in the initiation of Type-1 diabetes mellitus (T1DM) in both WT and NLRX1-deficient mice." (PMID 30908533, 2019). "We believe that this may further demonstrate how NLRX1 differs from other NLRs and PRRs that do play a role in diabetes and DN." (PMID 30908533, 2019). "A role for NLRX1 in diabetes and DN may, in fact, be better explored in a T2DM model, as type 2 diabetes is often associated with obesity." (PMID 30908533, 2019). "This study aimed to determine whether NLRX1 played a role in the development of diabetes and DN after multiple low-dose STZ treatment." (PMID 30908533, 2019). "We do acknowledge the significant decrease in NLRX1 mRNA expression observed in WT mice upon diabetes but are hesitant to presume that this may indicate a, yet unknown, role for NLRX1 in diabetes or DN." (PMID 30908533, 2019). "Furthermore, the effect of diabetes on NLRX1 expression was examined in WT mice." (PMID 30908533, 2019). "Based on the evidence gathered in this study, we conclude that NLRX1 does not mediate diabetes and diabetes-induced nephropathy in mice after multiple low doses of STZ." (PMID 30908533, 2019). "The present findings show that NLRX1 does not mediate the development of streptozotocin-induced diabetes and diabetic-induced nephropathy in mice after multiple low doses of streptozotocin." (PMID 30908533, 2019). "Our results show that the lack of NLRX1 does not affect the development nor severity of diabetes and DN." (PMID 30908533, 2019). "Based on this view, the NLRX1-driven propensity to metabolize glucose through glycolysis rather than OXPHOS would protect against diabetes and DN by increasing glucose expenditure and reducing oxidative stress levels." (PMID 30908533, 2019).
fungal infection (2 papers, 2020 to 2021). "Upon fungal infection of mice by Aspergillus fumigatus, NLRX1 deficiency resulted in increased pulmonary inflammation and immune cell recruitment as a result of excess production of chemokines and cytokines by airway epithelial cells." (PMID 33525671, 2021). "Following fungal infection of mouse peritoneal macrophages, it was found that NLRX1 bound to TUFM and induced ATG5-ATG12 complex formation and promoted LC3-II incorporation into the fungus containing phagosomes." (PMID 33525671, 2021). "Upon bacterial or fungal infection of myeloid cells, the ROS and autophagy modulating abilities of NLRX1 are predominated." (PMID 33525671, 2021). "Here we present Nlrx1 as a prospective host-targeted therapeutic for fungal infections that is involved in regulating the intensity and type of immune response to A. fumigatus in several pre-clinical models of IPA." (PMID 32956405, 2020). "In this study we describe the novel importance of Nlrx1 in controlling and fighting fungal infections in two different host cell populations through two distinct mechanisms." (PMID 32956405, 2020). "Based on these findings and our prior RNA-Seq analysis, we became interested in Nlrx1 as a regulator of immune signaling in response to fungal infections, specifically invasive pulmonary aspergillosis." (PMID 32956405, 2020). "The role of multi-faceted immune modulators, such as Nlrx1, provides a unique avenue to understand how biological processes such as immune signaling, metabolism, reactive oxygen species production and cell fate are interrelated in response to fungal infection." (PMID 32956405, 2020). "Apart from canonical autophagy, NLRX1 also promotes the non-canonical form of autophagy, termed microtubule-associated protein 1 light chain 3 (LC3)-associated phagocytosis (LAP) upon fungal infection." (PMID 33525671, 2021).
head and neck squamous cell carcinoma (2 papers, 2023). A squamous cell carcinoma that arises from any of the following anatomic sites: lip and oral cavity, nasal cavity, paranasal sinuses, pharynx, larynx, and salivary glands. "Additionally, in a model of HPV+ head and neck squamous cell carcinoma (HNSCC), NLRX1 interacts with and degrades STING to decrease IFN-I production and therefore limits tumor control." (PMID 37342194, 2023). "However, an in vitro study has shown that the HPV16 E7 protein can interact with NLRX1 and increase STING sensor turnover, leading to a reduction in the interferon response and the development and progression of head and neck squamous cell carcinoma (HNSCC)." (PMID 36831674, 2023).
Hepatic steatosis (2 papers, 2023 to 2025). Steatosis is a term used to denote lipid accumulation within hepatocytes. "Studies have shown that down-regulating NOD-like receptor (NLR) X1 (NLRX1) can inhibit glycolysis, enhance fat oxidation and reduce hepatic steatosis." (PMID 37663261, 2023). "Other research has found that knocking down NOD-like receptor (NLR) X1 (NLRX1) can suppress glycolysis and enhance fatty acid oxidation, thereby reducing hepatic steatosis." (PMID 40722708, 2025).
Hyperglycemia (2 papers, 2019). An increased concentration of glucose in the blood. "They reported that NLRX1-deficient mice were partially protected from the development of the diet-induced hyperglycemia based on fasting glucose and insulin levels, as well as glucose tolerance." (PMID 30908533, 2019). "Decreased expression of NLRX1 may be protective against diet-induced hyperglycemia due to decreased pancreatic lipid accumulation." (PMID 31681307, 2019). "We found that multiple low doses of streptozotocin induced body weight loss, polydipsia, hyperglycemia, glycosuria, and a mild DN phenotype in wildtype and NLRX1-deficient mice, without significant differences between these mouse strains." (PMID 30908533, 2019).
injury (2 papers, 2021 to 2023). Damage inflicted on the body as the direct or indirect result of an external force, with or without disruption of structural continuity. "The loss of NLRX1, which can negatively regulate NF-kB signaling, was found to exacerbate neural tissue damage in an animal model of brain injury." (PMID 38042785, 2023).
neuroblastoma (2 papers, 2019 to 2020). Neuroblastoma (NB) is the most common solid, extracranial childhood tumor. "In NLRX1 knock-in (KI) neuroblastoma cells, NLRX1 associated with GTPase dynamin-related protein 1 (DRP1), a major regulator of mitochondrial dynamics, resulted in increased mitochondrial fission, and the mitochondria in these cells showed morphological abnormalities." (PMID 33344269, 2020). "This resulted in increased cytotoxicity of Nlrx1−/− glia, as conditioned medium from Nlrx1−/− cultures induced significantly more cell death in N2A neuroblastoma and MO3.13 oligodendrocyte cell lines." (PMID 31525189, 2019).
pulmonary fungal disease (2 papers, 2020 to 2021). "We have previously shown that Nlrx1 is a critical regulator of immune signaling and mortality in several models of pulmonary fungal infection using the clinically relevant fungus Aspergillus fumigatus." (PMID 34790195, 2021). "In context to fungal pulmonary infections, our results show that Nlrx1 plays significant roles in host defense via PPP modulation of several aspects of metabolism, particularly glycolysis, to facilitate conidia processing in addition to its critical role in regulating immune signaling." (PMID 34790195, 2021). "Nlrx1 may function as a future target to mitigate inflammation and immunopathogenesis during fungal pulmonary infection as well as enhance beneficial neutrophil recruitment." (PMID 32956405, 2020). "Identifying appropriate small molecule therapeutics targeting Nlrx1 may show efficacy in combating IPA and potentially other forms of pulmonary fungal disease." (PMID 32956405, 2020).
renal fibrosis (2 papers, 2023 to 2025). A final common manifestation of a wide variety of chronic kidney diseases characterized by glomerulosclerosis and tubulointerstitial fibrosis. "In vivo, WT and NLRX1 KO mice were subjected to unilateral ureter obstruction (UUO) surgery to induce renal fibrosis." (PMID 38201227, 2023). "This merits further investigation to comprehensively understand how NLRX1 affects macrophage metabolism and function in the progression of renal fibrosis." (PMID 38201227, 2023). "Our results underscore the significant role of NLRX1 in the immune–metabolic regulation of macrophages, controlling both their polarization and function and as a protective factor against excessive renal fibrosis." (PMID 38201227, 2023). "Given the involvement of macrophages in the development of renal fibrosis, we next investigated the role of NLRX1 in the UUO model." (PMID 38201227, 2023). "As such, NLRX1 may be an attractive novel therapeutic target for renal fibrosis and fibrotic diseases in general." (PMID 38201227, 2023). "Given the pivotal role of macrophages in renal fibrosis and the protective role of NLRX1 in several preclinical model of fibrosis, we investigated whether NLRX1 influenced the progression of renal fibrosis in chronic obstructive nephropathy." (PMID 38201227, 2023). "Together, these data show that renal levels of TGFβ and multiple markers of renal fibrosis are increased in the absence of NLRX1 during UUO." (PMID 38201227, 2023). "The specific impact of NLRX1 on macrophages and its involvement in renal fibrosis is not fully understood." (PMID 38201227, 2023). "We then reasoned that the immunometabolic characteristics of macrophages lacking NLRX1, as observed in our in vitro experiment could potentially influence the progression of renal fibrosis." (PMID 38201227, 2023).
Sepsis (2 papers, 2022 to 2026). Sepsis is defined as life-threatening organ dysfunction caused by a dysregulated host response to infection. "A murine model of sepsis-induced ALI was established using cecal ligation and puncture (CLP), with NLRX1 overexpression achieved through adeno-associated virus serotype 9 (AAV9)-mediated gene delivery." (PMID 42078926, 2026).
acute lung injury (1 paper, 2023). A condition of lung damage that is characterized by bilateral pulmonary infiltrates (pulmonary edema) rich in neutrophils, and in the absence of clinical heart failure. "Nucleotide-binding domain and leucine-rich-repeat-containing family member X1 (NLRX1) is localized in mitochondria and involved in production of reactive oxygen species, inflammation, and apoptosis, which are the features of hyperoxic acute lung injury (HALI)." (PMID 36859435, 2023).
aneurysm (1 paper, 2025). Bulging or ballooning in an area of an artery secondary to arterial wall weakening. "In human patients, a significant downregulation of NLRX1 was observed in brain injury following aneurysm." (PMID 39875919, 2025).
breast tumor (1 paper, 2023). "In another cell line, MDA-MB-231 (human ER/PR- breast tumor cells), the knockdown of NLRX1 was consistent with our results regarding ROS levels." (PMID 37342194, 2023). "Likewise, the overexpression of NLRX1 in HEK293 (human embryonic kidney cells), MCF-7 (human ER/PR+ breast tumor cells), and HeLa (human cervical carcinoma cells) cell lines increased cell death and decreased ATP production." (PMID 37342194, 2023).
cardiac ischemia (1 paper, 2025). "Given that specific NLRX1 agonists are currently in development evaluating these compounds within the recently established small-animal multicenter consortium—designed to test cardioprotective agents against acute cardiac ischemia–reperfusion injury (IRl) appears to be a valuable approach." (PMID 40536683, 2025).
celiac disease (1 paper, 2023). An autoimmune genetic disorder with an unknown pattern of inheritance that primarily affects the digestive tract. "A study carrying out transcriptomic analysis showed significantly downregulated NLRX1 signaling in celiac disease patients, suggesting a potential correlation between the NLRX1 signaling pathway and gluten sensitivity." (PMID 37833958, 2023).
Cerebral ischemia (1 paper, 2025). Restriction of arterial blood supply to the brain associated with insufficient oxygenation to support the metabolic requirements of the tissue. "Notably, NOD-like receptor X1 (NLRX1) has emerged as a key autophagy-promoting factor that alleviates cerebral ischemia/reperfusion-induced neuronal injury." (PMID 41007413, 2025).
chlamydial infection (1 paper, 2023). "On the other hand, other studies report that NLRX1 amplifies NF-κB responses by inducing ROS production, and that NLRX1 enhances ROS production, which favors chlamydial infection." (PMID 37006312, 2023).
cholangiocarcinoma (1 paper, 2023). A carcinoma that arises from the intrahepatic biliary tree (intrahepatic cholangiocarcinoma) or from the junction, or adjacent to the junction, of the right and left hepatic ducts (hilar cholangiocarcinoma). "RiskScore of cholangiocarcinoma patients with 10 genes calculated followed the formula: The RiskScore=0.429*VEGFC -0.434*NFKBIA-0.884*NLRX1+0.54*AKT1+0.629*CSRP1+0.406*EPO+0.833*IL31RA+1.023*LEP+0.341*MUC4+0.363*SEMA4B." (PMID 36817485, 2023).
COVID-19 (1 paper, 2024). A disease caused by infection with severe acute respiratory syndrome coronavirus 2. "One of the gatekeepers that regulates mitochondrial-inflammasome interdependencies is the mitochondrial protein NLRX1, a member of the NOD-like receptor family and a potent pattern recognition receptor; it also affects the inflammatory response in COVID-19." (PMID 38974521, 2024).
histiocytic sarcoma (1 paper, 2016). An aggressive malignant neoplasm with a poor response to therapy, usually presenting as stage III/IV disease. "Together with the gene expression findings, these data show that NLRX1 attenuates inflammation and tumorigenesis through the negative regulation of genes associated with cancer, autophagy, and cell death during histiocytic sarcoma." (PMID 27105514, 2016). "Our data reveal that Nlrx1−/− mice are sensitive to urethane treatment and develop histiocytic sarcoma in the spleen that is associated with increased NF-λB signaling." (PMID 27105514, 2016). "Based on these results, our data suggests that macrophages are the dominate cell population associated with histiocytic sarcoma in the Nlrx1−/− mice." (PMID 27105514, 2016). "Together, these data suggest that NLRX1 functions to attenuate histiocytic sarcoma induced by urethane and further support a role for this unique NLR in tumor suppression." (PMID 27105514, 2016). "Additional mechanistic insight will be necessary to better define the relationship between NLRX1, IL-6 and histiocytic sarcoma pathogenesis." (PMID 27105514, 2016). "We also identify a diverse range of genes associated with common cancer pathways, AKT signaling, cell death, and autophagy that are also significantly up-regulated in the Nlrx1−/− mice during histiocytic sarcoma." (PMID 27105514, 2016). "This initial evaluation revealed that 64 genes associated with tumorigenesis were significantly up-regulated in Nlrx1−/− spleens with histiocytic sarcoma compared to the wild type." (PMID 27105514, 2016). "Collectively, our results further confirm that NLRX1 functions as a tumor suppressor and extends these findings to histiocytic sarcoma, which is an understudied cancer with few biomarkers." (PMID 27105514, 2016). "Together, these data show that NLRX1 suppresses tumorigenesis and reveals new genetic pathways involved in the pathobiology of histiocytic sarcoma." (PMID 27105514, 2016). "While we did not observe any role for dysregulated IFN signaling in the development of histiocytic sarcoma in the Nlrx1−/− mice, we did find a strong correlation between tumorigenesis and the up-regulation of genes associated with NF-λB signaling." (PMID 27105514, 2016). "Our study identified 44 genes associated with cell death that were upregulated in the spleens of Nlrx1−/− mice with histiocytic sarcoma." (PMID 27105514, 2016). "The increased Nlrx1−/− macrophage proliferation is consistent with the increased splenic macrophage proliferation observed by histopathology in the spleens during histiocytic sarcoma." (PMID 27105514, 2016). "The IPA analysis confirmed that the NF-λB signaling pathway was significantly up-regulated during histiocytic sarcoma in the Nlrx1−/− mice." (PMID 27105514, 2016). "Following urethane treatment, Nlrx1 expression was increased in wild type animals that were resistant to histiocytic sarcoma." (PMID 27105514, 2016). "Likewise, Ccl2 appears to be up-regulated in macrophages from Nlrx1−/− mice and was identified as being one of the genes with the greatest level of up-regulation in the spleen during histiocytic sarcoma." (PMID 27105514, 2016). "Based on these prior findings, we hypothesized that NLRX1 would function to inhibit tumorigenesis and thus the development of histiocytic sarcoma." (PMID 27105514, 2016). "The fact that NLRX1 is downregulated in this neoplasm may suggest a similar pattern in human histiocytic sarcoma." (PMID 27105514, 2016). "Many interesting targets were identified that have not been previously associated with either histiocytic sarcoma or NLRX1 function." (PMID 27105514, 2016). "Thus, in the current study, we have identified NLRX1 as an important tumor suppressor and characterized a group of genes downstream of NF-λB signaling that are significantly up-regulated in the Nlrx1−/− animals that contribute to the development of histiocytic sarcoma." (PMID 27105514, 2016).
histiocytic sarcoma (continued). "While no human histiocytic sarcoma studies have been conducted, NLRX1 gene expression data was evaluated for malignant fibrous histiocytoma." (PMID 27105514, 2016). "Each pathway downstream of AKT signaling was found to be up-regulated in the absence of NLRX1 during histiocytic sarcoma." (PMID 27105514, 2016). "Thus, IFN signaling does not appear to play a role in either histiocytic sarcoma or NLRX1 function in this model." (PMID 27105514, 2016).
hypoxic-ischemic encephalopathy (1 paper, 2024). "In a neonatal hypoxic-ischemic encephalopathy model, intraperitoneal injection of MT (15 mg/kg) into pups 1 h before hypoxia induction upregulated the expression of NLRX1, which downregulated mTOR expression and promoted ATG7 and Beclin-1 expression to promote mitophagy and inhibit apoptosis." (PMID 38786094, 2024).
intestinal tumour (1 paper, 2021). "Nevertheless, these reports indicate that NLRX1 has roles in suppressing intestinal tumour formation with functions directly attributed to IEC-intrinsic NLRX1 expression." (PMID 34854889, 2021).
intracranial aneurysms (1 paper, 2024). "Decreased NLRX1 expression was observed in human intracranial aneurysms and in hypoxic cardiomyocytes, kidney, brain and intestine." (PMID 38671928, 2024).
ischemia reperfusion injury (1 paper, 2019). Adverse functional, metabolic, or structural changes in ischemic tissues resulting from the restoration of blood flow to the tissue (reperfusion), including swelling; hemorrhage; necrosis; and damage from free radicals. "However, it is currently known that NLRX1 regulates OXPHOS and cell integrity in a model of ischemia-reperfusion injury, and that loss of NLRX1 increases oxygen consumption and oxidative stress in epithelial cells." (PMID 31058096, 2019).
malignant melanoma (1 paper, 2016). "When viewed in combination, these studies demonstrate that the spread of malignant melanoma is associated with decreased expression of essential components of the RLH pathway and heightened expression of the RLH/MAVS inhibitor NLRX1." (PMID 27198666, 2016).